IL6 (interleukin 6)
Diseases named in the same sentence as IL6 in open-access papers (continued):
Sharing a sentence is not in itself a finding about the gene and the disease.
tumor (continued). "In silico analyses confirmed the transcriptional upregulation of IL6 and RBP4 in CRC and revealed distinct molecular pathways—immune/inflammatory signaling for IL-6 and developmental signaling for RBP4—highlighting their possible contributions to tumor biology." (PMID 41007818, 2025). "Upon activation of the IL-6/JAK/STAT3 signaling pathway, the expression of genes such as Cyclin D1 and Bcl-2 is upregulated, promoting tumor cell cycle progression and inhibiting apoptosis, thereby enhancing tumor cell proliferation and survival." (PMID 40909292, 2025). "The tumor microenvironment releases proinflammatory cytokines, including TNF-α and IL-6." (PMID 41002580, 2025). "Additionally, systemic HT has been shown to influence the activity of the proinflammatory cytokine IL-6 within the TME, potentially diminishing its role in tumor progression." (PMID 40092992, 2025). "The differentiation of CAFs is crucial for cancer initiation and progression, and it is regulated by signaling pathways induced by tumor cell-derived TGF-β, EGF, PDGFα, PDGFβ, basic fibroblast growth factor (bFGF, also known as FGF2), interleukin 6 (IL-6), and interleukin 1β (IL-1β)." (PMID 40750884, 2025). "Additionally, pectin, particularly MCP, has been shown to decrease the levels of proinflammatory cytokines such as IL-6, TNF-α and IL-1β, which are often elevated in the tumor microenvironment and contribute to tumor progression." (PMID 41249064, 2025). "This pathway not only supports tumor growth despite CDK4/6 blockade but also contributes to a more aggressive and therapy-resistant phenotype, underscoring the therapeutic potential of dual inhibition strategies targeting both CDK4/6 and IL-6/STAT3 in TNBC." (PMID 41148817, 2025). "Here, we showed that lung fibroblast activated by DKK1 actively produced IL-6 and CCL2, which are representative cytokines identified as the iCAF markers, which raise a notion that iCAFs are activated and promote tumor progression in high DKK1-expressing tumors." (PMID 40025612, 2025). "BC cells release G-CSF, IL-6, and TGF-β, promoting MDSC expansion and activation within the tumor." (PMID 40136652, 2025). "Environmental inflammatory factors such as TGF‐β1, chemokines, interleukin (IL)‐17, lipopolysaccharide, IL‐6, and HGF exist and play an important role in the regulation of non‐CSC acquired stemness or CSC maintenance stemness in the hepatic cancer cell tumor microenvironment (TME)." (PMID 41346572, 2025). "Chronic inflammation may drive thyroid cell proliferation and tumor formation through pro-inflammatory cytokines (e.g., TNF-α, IL-6) and vascular endothelial growth factor (VEGF)." (PMID 41409611, 2025). "Furthermore, P. gingivalis recruits myeloid cells, alters the tumor microenvironment, and increases the production of pro-inflammatory cytokines, such as TNF-α, IL-6, and IL-1β, thereby further driving tumor growth." (PMID 41473772, 2025). "The cytokine profile observed in this study, characterized by reduced IL-6 and IL-8 levels with increased TNF-α secretion, suggests that HYP-PDT shifts the tumor microenvironment from a STAT3-dependent pro-tumor state toward an NF-κB–driven pro-inflammatory response." (PMID 41226910, 2025). "Additionally, inflammatory cytokines like interleukin-6 (IL-6) and tumor necrosis factor-alpha (TNF-α), released by both the tumor and the immune response, contribute to increased clot formation." (PMID 39857281, 2025). "Subsequently, further in vivo assays indicated that CM from TAMs could increase the tumor growth of OSCC cells, and IL6-Ab or cryptotanshinone could reverse these effects." (PMID 39897030, 2025). "Tumor type segregation of correlation analysis showed STS tumor growth correlated significantly with increased serum levels of GM-CSF, IL-2, IL-6, IL-7, IL-18 & MCP-1, whereas increased circulatory CD4+ and CD8+ T cells numbers correlated with STS tumor regression with CPMV treatment." (PMID 40386779, 2025).
tumor (continued). "Functionally, myCAFs promote tumor invasion by enhancing ECM deposition and remodeling matrix mechanics, whereas iCAFs modulate the immune microenvironment by secreting inflammatory factors, such as IL6 and CXCL12, to support tumor growth." (PMID 41373733, 2025). "Furthermore, IL-6-mediated STAT3 activation induces the expression of S100A9, a factor that promotes tumor invasion and metastasis." (PMID 41409248, 2025). "However, emerging research suggests that paclitaxel chemotherapy promotes the infiltration of M2 macrophages and tumor-acclimated neutrophils into the TME, implying a connection between dormancy and the IL-6/G-CSF and MEK/ERK signaling pathways." (PMID 40977686, 2025). "Furthermore, UA modulates the inflammatory tumor microenvironment by downregulating the expression of proinflammatory cytokines, such as IL-6 and TNF-α, which play crucial roles in tumor growth and metastasis." (PMID 40568370, 2025). "Among them, CAFs can promote tumor proliferation, migration and drug resistance by activating PI3K/AKT, STAT3 and other pathways through secreting CXCL12, IL-6, etc., and form a pro-cancer positive feedback loop with immunosuppressive cells such as MDSC and TAM." (PMID 40860340, 2025). "They demonstrated that tumor exosomal cSERPINE2 from breast cancer could upregulate MALT1 in TAMs, which then activated the NF-κB and increased the secretion of IL-6 by TAMs." (PMID 40443670, 2025). "The precise source of IL-6 in the HNSCC TME is not clearly established because tumour cells, CAFs, and immune cells have all been shown to release IL-6 into the TME and even into peripheral blood." (PMID 39858048, 2025). "CAAs differ from “normal” adipocytes as they display fibroblast-like morphology, usually contain several dispersed small lipid droplets, and produce increased amounts of inflammatory cytokines IL-1β, IL-6, IL-8, TNF, chemokines (CCL2, CCL5), and leptin, which altogether facilitate tumor progression." (PMID 40940764, 2025). "In addition, CAFs regulate the metabolic reprogramming of tumor cells by secreting cytokines such as CCL5, IL6, and CXCL10 in the rigid ECM environment." (PMID 40211368, 2025). "CD20+ subpopulation, known to secrete cytokines and chemokines that activate the STAT3/NF-κB signaling pathway, leading to increased expression of pro-inflammatory mediators, including IL-6, TNF-and IFN-γ, and MMP-9, which facilitate tumor invasion and metastasis." (PMID 40821783, 2025). "Moreover, CAFs significantly contribute to tumor invasion, angiogenesis, progression, and metastasis by secreting multiple growth factors and proinflammatory cytokines, such as VEGF, IL-6, CXCL12, and TGF-β." (PMID 40211368, 2025). "In the PBMC cultures, IL-10, TGF-γ, IL-6, and IL-1β cytokine levels were not detectable, suggesting that matrix alone without tumor tissue is not sufficient to induce production of these cytokines from immune cells." (PMID 40425576, 2025). "Further, serum cytokine levels, such as MCP-1, GM-CSF, IL-2, IL-6, IL-7 and IL-18, correlated with tumor growth independent of various treatments." (PMID 40386779, 2025). "In MSS CRC, myeloid cells that sense bacteria through toll-like receptors induce the secretion of calcineurin and IL-6, resulting in the expression of the co-inhibitory molecules B7H3 and B7H4 by tumor cells, thereby suppressing the anti-tumour response of CD8+T cells." (PMID 38305306, 2025). "Furthermore, IL-6 was recently shown to be overexpressed in TSC2 disease models, and inhibition with IL-6 antagonists was shown to reduce tumour growth." (PMID 41013689, 2025). "Similarly, in TAMs, the pathway can dictate polarisation fate: RMPs can promote anti‐tumour M1 polarisation, while in SPOP‐mutant PCa, NC‐STING signalling induces IL‐6 to drive pro‐tumour M2 polarisation." (PMID 41275427, 2025).
tumor (continued). "The immune changes of RFA are generally less than that of cryoablation, for example, in colon cancer murine model, cryoablation augmented secretion of a wider array of cytokines including interleukin (IL)-1β, IL-5, IL-6, and IL-10 than RFA, with both anti-tumor and anti-inflammatory profiles." (PMID 40264767, 2025). "The IL-6-dependent phenotype was attributed to protein interactions between STAT3 and stathmin, which stabilize microtubules—a mechanism potentially conserved across various systems, including retinal ganglion cells and tumor cells." (PMID 41514893, 2025). "Studies have found that IL-6 derived from PCa cells promotes the activation of CAFs, and the activated CAFs secrete metalloproteinases to promote the EMT of tumor cells, thereby enhancing tumor stemness." (PMID 39711287, 2025). "Furthermore, IL-6 or prostaglandin E2, which induces M2-TAM polarization by activating STAT3, STAT1, and STAT6 signaling pathways, can be secreted by tumor cells in response to cisplatin or carboplatin therapy." (PMID 40370720, 2025). "Tumor cells release various immunosuppressive molecules—such as TGF-β, IL-6, prostaglandin E2, chemokine ligand 2, and colony-stimulating factor 1—which can suppress CD8+ T cell function and facilitate the recruitment of immunosuppressive cells, reviewed elsewhere." (PMID 41023740, 2025). "This dysregulation is particularly pronounced in HIV-HL patients presenting with bulky disease, who demonstrate significantly higher IL-2R (p=0.04) and IL-6 (p=0.03) compared to HIV-positive patients without bulky tumor burden." (PMID 40969752, 2025). "NF-κB activation triggers inflammatory pathways, establishing a positive feedback loop with a rise in chemokine expression (e.g., CXCL8 and CCL2), nitric oxide synthase (NOS), COX-2, and inflammatory mediators (IL-6, IL-8, and TNF-α), thereby fostering tumor development." (PMID 40420174, 2025). "Additionally, it has been demonstrated that MSCs stimulate tumor angiogenesis by releasing bFGF, VEGF, FGF-2, IL-8, IL-6, IGF-1, TNF, and TGF β." (PMID 39974358, 2025). "Additionally, METTL14 is involved in regulating TNF‐related genes, IFN‐related pathways in tumors, IL‐6‐induced inflammation, and MHC class I‐mediated tumor immune escape." (PMID 41316520, 2025). "Except for IL-2, GM-CSF, IL-6, and IL-18 showed a negative correlation with tumor growth in CRT-NP treated patients." (PMID 40386779, 2025). "Moreover, IL-6 promotes angiogenesis, enhances cancer cell motility through hepatocyte growth factor (HGF) signaling, and impairs anti-tumor immunity by generating dysfunctional natural killer (NK) cells." (PMID 41007818, 2025). "Moreover, the newly induced SASP characteristics by IFI30 knockdown, including elevated levels of IL‐6, IL‐8, and TNF‐α, as well as decreased levels of TGF‐β and MMP‐9, reflect the dynamic interplay between senescence and tumor suppression." (PMID 40186402, 2025). "Notably, the synergy of anti-PD1, anti-IL-6, and AMD3100 resulted in attenuated tumor growth, even in intrinsically immunotherapy-resistant tumors." (PMID 40822347, 2025). "Through different time points analysis, we found that MSA-2 significantly stimulated TNF-α, IL-10, IL-6 and INF-β expression in both plasma and tumor and this expression reached the highest level around 4–6 days after MSA-2 injection and down to normal spectrum after 16 days." (PMID 38592428, 2024). "IL-6, IL-8 have been reported to induce chemoresistance in cancer through activation of the Jak2/Stat3 signaling pathway, activation of Stat3 can further promote VEGF expression and induce tumor angiogenesis." (PMID 39193386, 2024). "Meanwhile, the TME in colorectal cancer often shows a prominent inflammatory component with pro-inflammatory cytokines such as IL-6 and transforming growth factor alpha (TNF-α), which can promote tumor cell proliferation and survival through the activation of the STAT3 and NF-κB pathways." (PMID 39449800, 2024).
tumor (continued). "In addition, IL6 and CCR2 were among the top 10 most upregulated DEGs in HPV − tumor cells compared with HPV + tumor cells." (PMID 38468260, 2024). "Overall, positive associations between IL-6, IL-10, TNF-α, and inflammatory scores with all-cause mortality were evident among cases with non-triple-negative tumours but not among those with triple-negative tumours." (PMID 39342063, 2024). "Post-treatment, the tumor microenvironment showed immunomodulatory changes, including altered macrophage infiltration and significant gene expression changes related to inflammation and immune response, such as IDO1, IL-6, TNF, CD209, and FOXP3." (PMID 39765586, 2024). "This reduction is thought to inhibit tumor proliferation and prevent the secretion of several pro-inflammatory cytokines such as IL-17 and IL-6 (not measured in this study)." (PMID 38818375, 2024). "The tumor‐MDSC axis involving IL‐6 trans‐signaling can increase cancer cell aggressiveness in primary tumor locations and the metastasis to the lung by upregulating IL‐6 and sIL‐6Rα production." (PMID 38703051, 2024). "Importantly, autophagy inhibition has been shown to negatively affect the migration (metastasis) and stemness of CSCs and the secretion of a key tumor-promoting and CSC-maintaining cytokine, IL-6." (PMID 39201332, 2024). "Inhibition of IL-6R, PD-L1 or EGFR resulted in CXCL7 decline, and shCXCL7 decreased MCT-1, IL-6/IL-6R, p-EGFR and PD-L1, which may potentiate therapeutic efficacy against tumor spreading via lymphatic circulation." (PMID 38505617, 2024). "IL-6/IL-6R/GP130 signaling is responsible for innate and acquired immune responses but is frequently hijacked in multiple cancer types to promote anti-immune evasion and a pro-inflammatory tumor microenvironment." (PMID 39768178, 2024). "IL-4 and IL-6 have been used to stimulate the differentiation of CD163+ M2-like TAMs from primary human monocytes, and conditioned media from these resulting TAMs increased HNC tumor cell migration, invasion, and angiogenesis in vitro." (PMID 38468824, 2024). "In addition, tumour-derived cytokines such as TGF-β, IL-10 and IL-6 have been shown to inhibit DC survival and proliferation." (PMID 38384463, 2024). "For example, IL-6 signaling facilitates the progression of pre-neoplastic lesions to malignant forms, and negative feedback by SOCS3 proteins was found to decrease primary tumor growth." (PMID 38141171, 2024). "Activation of the cGAS/STING pathway and production of immunomodulatory molecules such as INF-α, IL-6, CXCL9 and CXCL10 were described to be involved in the enhanced migration of immune cells in cancer, particularly macrophages, and regulate anti-tumor immune response." (PMID 38587186, 2024). "Gene expression for IL-1α, IL-1β, IL-6, IL-12, IL-23, CCL8, CXCL8, and TNF-α was significantly higher in the second-generation group, and a higher secretion of IL-6, IL-12, IL-23 and TNF-α was confirmed in the supernatant after 24 h of tumor cell co-cultivation in vitro." (PMID 39061247, 2024). "In addition, IL-6 is regarded as a major regulator of MDSC accumulation and activation, which is capable of promoting tumor cell proliferation and metastasis." (PMID 39735340, 2024). "Furthermore, administration of a histamine antagonist reduced IL6/STAT3 signaling and suppressed tumor growth." (PMID 39840030, 2024). "Likewise, other pro-inflammatory cytokines such as IL-6, IL-1, and TNF-α also can drive stem-cell like transition via EMT pathway in high-grade gliomas, leading to GSC-related tumor progression and therapy resistance." (PMID 38890642, 2024).
tumor (continued). "In addition, experimental studies in a variety of murine tumor models, including HCC models, have demonstrated the potential of targeting IL-6 in conjunction with PD-1/PD-L1 blockade to reverse ICI resistance." (PMID 39335733, 2024). "Moreover, ROS activate the mitogen-activated protein kinase (MAPK) pathway, which drives the production of pro-inflammatory cytokines like IL-1, IL-6, TNF-α, and TGF-β, leading to nuclear factor-kappa B (NF-κB) activation and tumor proliferation." (PMID 39766214, 2024). "Its activation leads to increased secretion of pro-inflammatory cytokines such as IL-6, IL-1β, and TNF-α, which may promote inflammation and support a pro-tumor environment." (PMID 39273213, 2024). "Hypoxia in glioblatoma associates with complex signaling patterns including activation of several pathways such as MAPK, PI3K-AKT/mTOR and IL-6/JAK/STAT3 with the master regulator HIF-1, which in turn drive particular tumor behaviors determining, in the end, treatment outcomes and patients fate." (PMID 38654280, 2024). "Notably, PEG-MnMOF@PTX demonstrated potent induction of proinflammatory factors TNF-α and IL-6 secretion, along with TGI evidenced by a tumor suppression of up to 84.4% and a substantial improvement in survival." (PMID 38715912, 2024). "Moreover, solanine significantly downregulates key inflammatory and proliferative markers, such as iNOS, IL-6, Cyclin D1, and PCNA, reducing tumor growth and inflammation." (PMID 39124760, 2024). "In the HCC tumor microenvironment, chemokines and cytokines, such as stromal cell-derived factor 1 alpha (SDF-1α, CXCL12a) and IL-6, can induce MDSC infiltration and activation (IL-6/STAT3-mediated) to suppress the antitumor immune response and promote tumor progression." (PMID 38397901, 2024). "IL-6 secreted by tumor fibroblasts induces activation of the Janus kinase/signal transducer and activator of transcription (JAK/STAT) pathway in tumor cells, which promotes the expression of c-Myc, thereby facilitating EC cell proliferation in vitro and in vivo." (PMID 38778089, 2024). "In contrast, other reports suggest that IL-6 does not affect the growth of OSCC cell lines but influences tumor growth and progression by promoting surrounding lymphangiogenesis and angiogenesis." (PMID 38510850, 2024). "In CD8+ T cells, IL6 upregulates immune checkpoints like PD-1, diminishing cytotoxic function and reducing the production of key cytokines, such as interferon-gamma (IFN-γ), thereby impairing anti-tumor responses." (PMID 39766086, 2024). "The activation of the stat signaling pathway by IL-6 may lead to the differentiation of CD73+γδ Tregs and subsequently impair the tumor-killing function of CD8+ T cells." (PMID 38426090, 2024). "Extracellularly, in the tumor microenvironment, S100A4 interacts with RAGE in a paracrine manner, This interaction subsequently induces the release of pro-inflammatory factors IL-6, IL-8 and CXC-L10 which then convert monocytes into TAMs." (PMID 39830522, 2024). "Several additional murine studies highlight the potential for improved anti-tumor response with combination therapy using anti-IL-6 with ICI, suggesting IL-6 blockade could decouple ICI anti-tumor immunity from toxicity." (PMID 39737191, 2024). "In addition, tumor cell-derived conditioned medium (CM) containing abundant extracellular vesicles also increased α-SMA, FAP, IL-1, IL-6, IL-8, CCL5 and CXCL12 expression and enhanced the proliferation, motility and invasion of ADSCs." (PMID 38233863, 2024). "The hypothesis predicts that blockade of IL-6 and its companion cytokines, TNF-α, and IL-1β, will convert an immunologically “cold” (unresponsive) tumor to one that is “hot” (immune responsive)." (PMID 39512605, 2024). "Although the TNFα level was not different in the tumor and the non-tumor groups (P > 0.9999), the IL-6 level was significantly high in the tumor group (P < 0.001)." (PMID 38166062, 2024).